ANLN (anillin, actin binding protein)
Description:
Required for cytokinesis. Essential for the structural integrity of the cleavage furrow and for completion of cleavage furrow ingression. Plays a role in bleb assembly during metaphase and anaphase of mitosis. May play a significant role in podocyte cell migration.
Synonyms: ANILLIN; Scraps; scra; FSGS8
Tractability: Small molecule: a structure with a bound ligand is known. PROTAC: UniProt records ubiquitination sites on it; ubiquitination databases record sites on it.
Gene: Protein-coding gene on chromosome 7 (36,389,727 to 36,453,791, forward strand). Ensembl gene ENSG00000011426.
Subcellular location: Nucleus; Cytoplasm, cytoskeleton; Cytoplasm, cell cortex; Cell projection, bleb
Subcellular location (Human Protein Atlas): Nucleoplasm; Midbody
Pathways (Reactome):
Signal Transduction: RHOA GTPase cycle; RHOB GTPase cycle; RHOC GTPase cycle
Gene Ontology:
Molecular function: actin binding; cadherin binding
Biological process: mitotic cytokinesis; podocyte cell migration; positive regulation of bleb assembly; actomyosin contractile ring assembly; regulation of exit from mitosis; septin ring assembly; septin ring organization
Cellular component: actin cytoskeleton; actomyosin contractile ring; bleb; cell cortex; midbody; nucleoplasm; cytosol; cytoskeleton; nucleus
Genetic constraint (gnomAD): Loss-of-function variants: 46 observed, 109.55 expected, observed/expected ratio (o/e) 0.42, 90% interval 0.33 to 0.54. The upper end of that interval is the gene's LOEUF score, 0.54, which puts it in group 2 of 6, group 1 being the genes least tolerant of losing a copy. Missense variants: 1,065 observed, 1,238.7 expected, observed/expected ratio (o/e) 0.86, 90% interval 0.82 to 0.9. Synonymous variants: 368 observed, 429.97 expected, observed/expected ratio (o/e) 0.86, 90% interval 0.79 to 0.93.
Homologues: Orthologues: chimpanzee ANLN (99% identical), macaque ANLN (97% identical), pig ANLN (89% identical), dog ANLN (88% identical), rabbit ANLN (84% identical), guinea pig ANLN (82% identical), mouse Anln (80% identical), rat Anln (80% identical), rat Anlnl1 (72% identical), tropical clawed frog anln (55% identical), zebrafish anln (49% identical), Drosophila melanogaster scra (25% identical), and 3 more. Paralogues in human: RTKN (9% identical), RTKN2 (8% identical).
Diseases named in the same sentence as ANLN in open-access papers:
ANLN is named in the same sentence as 111 diseases in open-access papers, as found by Europe PMC text mining. Sharing a sentence is not in itself a finding about the gene and the disease. The quoted sentences say what the papers report.
breast carcinoma (53 papers, 2011 to 2026). "High ANLN expression is strongly associated with shorter overall survival, breast cancer-specific survival, and recurrence-free survival." (PMID 41573677, 2025). "An interesting study revealed that the rs3735400 variant in the ANLN gene inhibits cell proliferation and reduces breast cancer risk in BRCA1 mutation carriers." (PMID 41573677, 2025). "In breast cancer, limited studies have shown that the expression of ANLN is associated with a poor prognosis and promotes doxorubicin resistance." (PMID 35578283, 2022). "ANLN was associated with migration, growth, and metastasis of breast cancer cells through control of stemness and differentiation." (PMID 36362041, 2022). "Ten hub-key genes were identified, and survival analysis showed that UBE2T and ANLN were upregulated in breast cancer and their upregulation was associated with a poor prognosis." (PMID 35578283, 2022). "In breast cancer, ANLN upregulation markedly enhances the self-renewal potential of epithelial-type MCF10AneoT cells, whereas loss of ANLN decreases stem/progenitor properties of mesenchymal-type MDA-MB-231 and BT549 breast cancer cells." (PMID 35340220, 2022). "In the present study, immune cell infiltration analyses showed that Th1 was negatively associated with ANLN in all types of breast cancer, whereas it was positively associated with UBE2T in luminal A breast cancer." (PMID 35578283, 2022). "ANLN has been associated with chemoresistance in breast cancer, and its silencing can stimulate apoptosis, decrease cell viability of tumoral cells, and increase cleaved-caspase-3 protein level in TNBC cells." (PMID 34440380, 2021). "Here, our data proved that ANLN was over-expressed and negatively associated with a miR-153-3p level in LR breast cancer tissues." (PMID 34295807, 2021). "In breast cancer associated fibroblast, Hippo signaling regulates the expression of several cytoskeletal regulators including ANLN, to help remodel the extracellular matrix." (PMID 30103211, 2018). "Knockdown of ANLN protein caused an increase in senescent cells with large, poly-nucleated morphology and G2/M phase arrest in breast cancer cells." (PMID 30103211, 2018). "The result from the present study validates previous findings of high nuclear expression of ANLN being associated with a more aggressive breast cancer phenotype." (PMID 27863473, 2016). "O’Leary and co-workers found that a moderate to strong nuclear intensity of ANLN expression was significantly associated with decreased breast cancer specific survival (BCSS) and recurrence free survival (RFS)." (PMID 27863473, 2016). "Based on quantitative RNA-Seq data available from the Cancer Genome Atlas we showed that high levels of ANLN mRNA in breast cancer tissue were associated with shorter survival of patients as compared to patients with low levels of ANLN mRNA." (PMID 27863473, 2016). "ANLN mRNA abundance was associated with increased hazard of breast cancer death." (PMID 31636652, 2019). "Likewise, detection of nuclear ANLN was significantly associated with decreased breast cancer survival and recurrence-free survival." (PMID 28881803, 2017). "Highly expressed ANLN, plays an indispensable role in the structural integrity of the cleavage groove and the completion of cleavage groove ingression, might be the cause of breast cancer cell proliferation." (PMID 34743685, 2021). "For instance, high ANLN expression correlates with enhanced proliferation and migration capabilities of tumor cells in lung adenocarcinoma and breast cancer." (PMID 40666516, 2025). "In instances such as ANLN-depleted breast cancer lines, the presence of polynucleated cells was detected, and cell growth was suppressed." (PMID 39968094, 2025). "miR-16-5p inhibits proliferation, migration and invasion of breast cancer cells and suppresses breast cancer progression by targeting ANLN." (PMID 40764609, 2025).
breast carcinoma (continued). "ANLN promotes breast cancer progression by enhancing cell proliferation, migration, and invasiveness while inhibiting apoptosis, and it further contributes to disease development through genetic regulation and subtype-specific functions." (PMID 41573677, 2025). "ANLN is highly expressed in breast cancer cell lines and tissues, with its expression significantly correlated with tumor size, high tumor grade, Her2 status, and Ki-67 expression levels." (PMID 41573677, 2025). "Data from the TCGA database further indicated that ANLN is highly expressed in breast cancer and significantly correlates with overall and progression-free survival." (PMID 40346052, 2025). "Bioinformatics analysis has revealed that ANLN expression correlates with immune cell infiltration and the immunosuppressive microenvironment across various breast cancer subtypes." (PMID 41573677, 2025). "In breast cancer, ANLN was found to be a alternative marker for Ki-67 (cell proliferation index), which is consistent with our findings." (PMID 37007961, 2023). "ANLN is elevated in various TCGA and GTEx tumors, including hepatocellular carcinoma, pancreatic adenocarcinoma, and breast carcinoma, compared with paired normal tissues." (PMID 37007961, 2023). "An upregulation of ANLN (Anillin actin-binding protein) was identified in breast carcinoma and was a target of miR-16-5p in breast cancer cells." (PMID 37374977, 2023). "ANLN is overexpressed in different tumor types, including breast cancer, lung cancer, pancreatic cancer, liver cancer, bladder cancer, and colorectal cancer." (PMID 35991576, 2022). "Upregulation of the expression of ANLN and UBE2T is associated with a worse prognosis of breast cancer." (PMID 35578283, 2022). "ANLN and UBE2T upregulation was associated with the prevalence of Th1 and Th2 cells, shifting the Th1/Th2 balance to Th2 in Basal and Luminal-B breast cancers, which indicates a poor prognosis (P < 0.05)." (PMID 35578283, 2022). "Patients with breast cancer showed high ANLN expression in tumor tissues; moreover, ANLN downregulation affected the tumor cell cycle and promoted apoptosis while inhibiting tumor cell proliferation, migration, and invasion." (PMID 35991576, 2022). "ANLN downregulation inhibited cell migration and invasion in breast cancer, which was considered a biomarker for global genomic instability and to play a vital role in replicative immortality of tumor cells." (PMID 35444699, 2022). "We further identified corresponding targeting genes of TNBC-specific super-enhancers, including FOXC1, MET and ANLN, whose function and clinical relevance in breast cancer have been well documented." (PMID 34718356, 2022). "In breast cancer, ANLN was reported to affect the stemness and differentiation of MCF10AneoT cells, and we also observed significant correlations between ANLN expression with DNAss, and RNAss in many tumors." (PMID 36199577, 2022). "For example, ANLN silencing using lentivirus transfection inhibits proliferation, migration, and cell cycle progression in breast cancer cells." (PMID 35568883, 2022). "Taken together, these findings indicate that the expression of ANLN and UBE2T is associated with immune cell infiltration and the immunosuppressive microenvironment in different subtypes of breast cancer." (PMID 35578283, 2022). "Th2 was significantly positively associated with ANLN in TNBC and luminal B breast cancer and significantly positively associated with UBE2T in all subtypes of breast cancer." (PMID 35578283, 2022). "Our study showed that the phosphorylation level of ANLN was higher in some cancers, such as ovarian cancer, lung cancer, and breast cancer." (PMID 35340220, 2022). "As an actin-binding protein, ANLN has been presented to be frequently upregulated in some human cancers, including breast cancer." (PMID 34295807, 2021).
breast carcinoma (continued). "In non-small lung cancer and breast cancer lines, cell proliferation is suppressed and large-sized polynucleated cells form upon ANLN depletion." (PMID 33854062, 2021). "Using clinically annotated breast cancer gene expression datasets, we found that the percentage of cases with ANLN mRNA upregulation is significantly higher in TNBC as compared to luminal breast tumors." (PMID 33854062, 2021). "Subsequently, we further identify the influence of miR-153-3p expression on ANLN in LR-resistant breast cancer cells." (PMID 34295807, 2021). "Upregulation of ANLN leads to shorter survival time in patients with colorectal cancer and breast cancer." (PMID 34530829, 2021). "Increasing studies have shown that ANLN is highly expressed in multiple cancers, including breast cancer, ovarian cancer, kidney cancer, colorectal cancer, hepatocellular carcinoma, lung cancer, and pancreatic tumors." (PMID 34344861, 2021). "High levels of ANLN contributed to the poor prognosis of anthracycline-based chemotherapy in breast cancer patients." (PMID 34260414, 2021). "Knockout of ANLN leads to suppression of stemness and induction of mesenchymal-to-epithelial transdifferentiation, indicating that inhibiting ANLN expression hinders breast cancer cell migration and invasion." (PMID 34194957, 2021). "Subsequently, when ANLN was suppressed by siRNA or miR-16-5p was overexpressed by miRNA mimics, breast cancer cells induced apoptosis, also showing that miR-16-5p promoted apoptosis by regulating ANLN in breast cancer cells." (PMID 34743685, 2021). "Circ-MMP11 and ANLN were highly expressed, and miR-153-3p was decreased in LR breast cancer tissues and cells." (PMID 34295807, 2021). "Next, functional experiments on breast carcinoma cells were performed after transfection of the miR-16-5p mimic, si-ANLN and NC groups." (PMID 34743685, 2021). "Rare homozygotes in the ANLN (rs12535394) SNP pair are prognostic of favorable breast cancer survival." (PMID 34260414, 2021). "And circ-MMP11 functioned as a sponge of miR-153-3p to regulate ANLN expression, thereby promoting lapatinib resistance in breast cancer cells, providing therapeutic targets for the treatment of breast cancer." (PMID 34295807, 2021). "Consistently, western blot analysis displayed that ANLN protein level was increased in the drug-resistant tissues and LR-resistant breast cancer cells versus their respective controls." (PMID 34295807, 2021). "It has also been reported that breast cancer patients with high expression of ANLN have a poor prognosis." (PMID 34194957, 2021). "Besides, the expression of ANLN in breast cancer cells played an important role in cell division, and the high expression of ANLN in nuclear was associated with poor prognosis in breast cancer patients; thus, ANLN could be used as a prognostic marker in clinical practice." (PMID 32903581, 2020). "Previous studies demonstrated that the high protein abundance of ANLN was the predictive biomarker for multiple cancers such as breast cancer, lung squamous cell carcinoma, and prostate cancer." (PMID 32149105, 2020). "Owing to its critical role, studies have observed overexpressed ANLN in several types of cancers, and it has also been proven to be correlated with poor prognoses in breast cancer, lung cancer and hepatocellular carcinoma." (PMID 32966237, 2020). "Knockdown of ANLN by lentivirus inhibited breast cancer cell growth, and ANLN in primary breast cancer was documented as a potential biomarker of Ki-67, which substantially contributes to cell progression." (PMID 32560530, 2020). "We report that concomitant low ANLN and high KDR gene expression is associated with favorable breast cancer survival." (PMID 31636652, 2019). "This implicates that ANLN drove the main effect of this interaction and KDR has an amplification effect on ANLN functionalities in breast cancer." (PMID 31636652, 2019).
breast carcinoma (continued). "ANLN mRNA expression during tumor progression was measured in a diverse spectrum of tumors including breast cancers as well as normal tissues, which showed an increasing trend from the normal to the metastatic state." (PMID 31636652, 2019). "We did not observe any significant alteration on KDR gene expression when modulating that of ANLN in the luminal breast cancer cell line MCF7 and normal breast cell line MCF10A." (PMID 31636652, 2019). "The expression level of ANLN gene is closely related to the invasiveness of tumors, and it is highly expressed in various types of malignant tumors such as breast cancer, colon cancer, liver cancer and lung cancer." (PMID 31660264, 2019). "Externally modulating breast cancer cells towards low ANLN and high KDR gene expression can transit cells from the triple negative to luminal-like phenotype and sensitize cells to Tamoxifen treatment." (PMID 31636652, 2019). "In fact, elevated ANLN expression was observed in many other human cancers and ANLN expression was proposed to be a prognostic and therapeutic indicator for breast cancer, colorectal cancer, lung cancer and upper urinary tract urothelial carcinoma." (PMID 30103211, 2018). "A high fraction of nuclear ANLN expression in cancer cells was correlated with a poor prognosis in breast cancer patients." (PMID 30103211, 2018). "Previous studies have reported that ANLN depletion leads to an increased number of large, poly-nucleated tumor cells in breast cancer and non-small cell lung cancer." (PMID 30103211, 2018). "The impact of ANLN on persistence of estrogen receptor positive breast cancer was shown by respective experiments showing a cell-cycle arrest in G2/M, lowered expression of cyclins D1, A2, and B1, as well as altered cell morphology." (PMID 28914765, 2017). "Past studies showed that knockdown of ANLN expression in breast cancer cells arrested the cell cycle in S/G2 or G2/M transition." (PMID 28881803, 2017). "In cohort I, breast cancer patients with high ANLN NF had a significantly reduced OS (p = 0.022) and BCSS (p = 0.044)." (PMID 27863473, 2016). "In a recent study based on a cohort consisting of 71 patients diagnosed with primary breast cancer, the rate of ANLN expression was shown to be significantly higher in breast cancer compared to normal breast tissue." (PMID 27863473, 2016). "The aim of the present study was to further investigate and validate the prognostic significance of ANLN expression in breast cancer." (PMID 27863473, 2016). "The present study aimed at further examining the prognostic value and functional role of ANLN in breast cancer." (PMID 27863473, 2016). "Our results show that IHC-based ANLN expression provides a distinct and reproducible staining pattern, suggesting a role as supplement to the prognostic breast cancer biomarkers currently used in the clinic." (PMID 27863473, 2016). "The objective of the current study was to further explore the prognostic and functional value of ANLN as a single biomarker in breast cancer." (PMID 27863473, 2016). "Anillin (ANLN), an actin-binding protein required for cytokinesis, has recently been presented as part of a prognostic marker panel in breast cancer." (PMID 27863473, 2016). "The relevance of ANLN protein expression in breast cancer tissue specimens has been explored as a part of a systematic approach to identify novel prognostic biomarkers." (PMID 27863473, 2016). "Analysis of the mRNA sequencing data (RNA-Seq) in the Cancer Genome Atlas showed that breast cancer patients with high expression of ANLN in tumor tissue had a poorer prognosis as compared to patients with low levels of ANLN." (PMID 27863473, 2016). "The functional relevance of ANLN was investigated in two breast cancer cell lines using RNA interference." (PMID 27863473, 2016). "Two independent breast cancer patient cohorts were used to investigate the potential impact of ANLN expression on survival." (PMID 27863473, 2016).